NTRK2 (neurotrophic receptor tyrosine kinase 2)
Diseases named in the same sentence as NTRK2 in open-access papers (continued):
Sharing a sentence is not in itself a finding about the gene and the disease.
fibrosarcoma (2 papers, 2018 to 2024). A malignant mesenchymal fibroblastic neoplasm affecting the soft tissue and bone. "Of the NTRK fusion partners we identified in pediatrics, TPM3::NTRK1 (fibrosarcoma) has been documented in pediatrics by others, and DAB2IP::NTRK2 (primitive neuroectodermal tumor) has been previously documented in adults." (PMID 38967220, 2024).
ganglioglioma (2 papers, 2020 to 2023). A well differentiated, slow growing neuroepithelial neoplasm composed of neoplastic, mature ganglion cells and neoplastic glial cells. "The second fusion pattern starting from exon 15 of the NTRK2 had been identified in a ganglioglioma harboring TLE4-NTRK2 fusion." (PMID 37865792, 2023).
Infertility (2 papers, 2022). "Moreover, oocyte-specific deletion of the Ntrk2 (TrkB) gene revealed early adulthood infertility, with progressive post-pubertal depletion of oocytes accompanied by a loss of follicular organization." (PMID 35177657, 2022).
mesenchymal neoplasms (2 papers, 2021 to 2024). "Gene fusions involving the NTRK gene family (NTRK1, NTRK2, and NTRK3) are usually described in a broad spectrum of mesenchymal tumors." (PMID 37798904, 2024). "Fusions involving NTRK1, NTRK2, and NTRK3 are oncogenic drivers occurring in a spectrum of mesenchymal neoplasms ranging from benign to highly malignant tumors." (PMID 32860002, 2021).
neuroendocrine neoplasm (2 papers, 2022 to 2025). Endocrine tumors, also referred to as neuroendocrine tumors (NETs), are defined by a common phenotype which is characterized by the expression of general markers (neuron specific enolase, chromogranin, synaptophysin) and hormone secretion products. "However, mutations in various genes related to TKs were detected in the tumor samples (JAK3, NRAS, NTRK2, NF1, SETD2) suggesting frequent alteration of TK pathways for neuroendocrine neoplasms." (PMID 36743926, 2022).
oligodendroglioma (2 papers, 2023). A well-differentiated (WHO grade II), diffusely infiltrating neuroglial tumor, typically located in the cerebral hemispheres. "One of the ATRX-deficient samples with MMR-d (case #17) was a recurrent tumor showing oligodendroglioma-like morphology and harboring fusions involving the NTRK2 and LRRFIP2 genes." (PMID 37891325, 2023).
prostate tumor (2 papers, 2023 to 2024). "Module 3 includes NTRK2, DDR2, and STAT5B, which have been associated with prostate tumor metastasis, and JAZF1, ZEB1, and BCL2, which have been linked to cancer progression and resistance to chemotherapy." (PMID 39347576, 2024).
T-cell acute lymphoblastic leukemia (2 papers, 2016 to 2019). Acute lymphoblastic leukemia of T-cell origin. "Neurotrophic receptor tyrosine kinase 2 activation cooperates with PTEN deficiency through the activation of both the JAK–STAT3 and PI3K-AKT pathways to induce aggressiveness, resistance to current therapies and poor prognosis of T-cell acute lymphoblastic leukemia." (PMID 31245181, 2019).
uveal melanoma (2 papers, 2020 to 2024). A melanoma derived from melanocytes of the uveal tract. "Increased NTRK1 expression was a risk factor for uveal melanoma (UVM), and high NTRK2 and NTRK3 expression was associated deceased OS, DSS, and PFI in bladder urothelial carcinoma (BLCA)." (PMID 38357305, 2024).
ataxia telangiectasia (1 paper, 2024). Ataxia-telangiectasia is the association of severe combined immunodeficiency (affecting mainly the humoral immune response) with progressive cerebellar ataxia. "In addition, by exploring a publicly available transcriptomic dataset from the cerebella of healthy humans and patients with ataxia–telangiectasia (AT), we observed that NTRK2 expression was reduced in the GCs of AT cerebella, but not in PCs." (PMID 39194574, 2024).
bruxism (1 paper, 2021). Excessive clenching of the jaw and grinding of the teeth. "We aimed to study whether sequence variants in genes involved in stress regulation pathways: NTRK2 and BDNF, may be associated with awake bruxism susceptibility, clinical presentation, and patients’ perceived stress level." (PMID 34610834, 2021).
congenital mesoblastic nephroma (1 paper, 2022). A low grade childhood congenital malignant neoplasm arising from the kidney. "In tumors with a high frequency of NTRK rearrangements, such as infantile fibrosarcoma, congenital mesoblastic nephroma, and secretory breast carcinoma, NTRK1, NTRK2, and NTRK3 break-apart probes have been routinely used for the triple detection of FISH." (PMID 36612101, 2022).
cryptorchidism (1 paper, 2024). The failure of one or both testes of a male fetus to descend from the abdomen into the scrotum during the late part of pregnancy. "Second, this study should be further validated by in vivo animal experiments to reveal the relevance of NTRK2 to cryptorchidism and the molecular mechanism by which NTRK2 modulates circadian rhythms with noncoding RNA." (PMID 39769319, 2024). "qPCR, IHC/IF, and Western blot revealed that NTRK2 was involved in regulating the development of cryptorchidism and revealed the target sites of NTRK2." (PMID 39769319, 2024). "NTRK2 may affect the development of the testis by regulating the specific signaling pathways of related hormones, and cryptorchidism often has abnormalities in certain hormone signaling pathways." (PMID 39769319, 2024). "Further studies will help clarify the specific role NTRK2 plays in this biological process and whether it may be a new target for the treatment of cryptorchidism or related diseases." (PMID 39769319, 2024). "However, the specific regulatory mechanism of LncRNA-targeted NTRK2 involved in the circadian rhythm during the development of cryptorchidism in yaks requires further investigation." (PMID 39769319, 2024).
diabetic cardiomyopathy (1 paper, 2016). Diabetic cardiomyopathy is a disorder of the heart muscle in people with diabetes. "Moreover, down-regulation of Ntrk2 and Ntrk3 genes might also play a role in the development of diabetic cardiomyopathy." (PMID 27496100, 2016).
diffuse astrocytoma (1 paper, 2020). A low-grade (WHO grade II) astrocytic neoplasm. "FGFR1, NTRK2, MYB, and MYBL1 rearrangements: Among patients with diffuse astrocytomas who had testing for rearrangements of FGFR1 (n = 5), NTRK2 (n = 4), MYB (n = 2), or MYBL1 (n = 1) performed on both paired surgical specimens, results remained negative in all pairs, with no acquisition or loss." (PMID 33153497, 2020).
emotional dysregulation (1 paper, 2016). "However, no study has hitherto investigated the direct link between NTRK2 and emotional dysregulation in psychopathology, and our results allow inferences solely in healthy populations." (PMID 26978740, 2016).
esophageal adenocarcinoma (1 paper, 2025). A malignant tumor with glandular differentiation arising predominantly from Barrett mucosa in the lower third of the esophagus. "An oncogenic, canonical GNAQ-NTRK2 fusion identified in a patient with esophageal adenocarcinoma patient would have likely been missed as breakpoints within both genes were in intronic regions (intron 1 of GNAQ, intron 15 of NTRK2) that are not typically covered in DNA-only hybrid capture panels." (PMID 40385986, 2025).
hippocampal atrophy (1 paper, 2025). "Neuroimaging–genetic work extends this evidence, with NTRK2 rs1948308 carriers exhibiting smaller hippocampal volumes and increased resistance; mediation analyses confirm hippocampal atrophy as a biological pathway linking genotype to clinical outcome." (PMID 41465113, 2025).
intervertebral disc degeneration (1 paper, 2024). "Similarly, neurotrophic receptor tyrosine kinase 2, Ntrk2, was recently proposed as a prognostic gene for intervertebral disc degeneration, supporting its upregulation in this degenerative context." (PMID 38510179, 2024).
lipoma (1 paper, 2022). A benign, usually painless, well-circumscribed lipomatous tumor composed of adipose tissue. "By utilizing targeted RNA next-generation sequencing (NGS), fluorescence in situ hybridization (FISH), reverse transcriptase PCR (RT-PCR), and Sanger sequencing, we verified an in-frame fusion between NTRK2 and the lipoma HMGIC fusion partner-like 3 (LHFPL3)." (PMID 36531047, 2022).
lymphoma (1 paper, 2024). A malignant (clonal) proliferation of B- lymphocytes or T- lymphocytes which involves the lymph nodes, bone marrow and/or extranodal sites. "Downregulation of miRNA-151 in DLBCL when using PBMC as control group was also found in human lymphoma in the regulation of target genes being associated with tumor cells such as the neurotrophic tyrosine receptor kinase 2 (NTRK2) gene." (PMID 38828367, 2024).
mastitis (1 paper, 2025). Inflammation of breast tissue during lactation or postpartum due to an obstructed duct or infection. "Candidate genes identified in Angus include the neurotrophic receptor tyrosine kinase 2 (NTRK2) that has been implicated with the sire conception rate in Holstein cattle, and MBL associated serine protease 2 (MASP2) was associated with mastitis and milk production in Chinese Holstein cattle." (PMID 40424241, 2025).
microcephaly (1 paper, 2023). A congenital or acquired developmental disorder in which the circumference of the head is smaller than normal for the person's age and sex. "Variants in NTRK2, the gene encoding the BDNF receptor TrkB, have been identified in patients presenting with microcephaly." (PMID 36845425, 2023).
morphine dependence (1 paper, 2020). Strong dependence, both physiological and emotional, upon morphine. "From this, it can be concluded that the treatment effect of sinomenine on morphine dependence may be related to the BDNF/Ntrk2 signaling pathway." (PMID 32670209, 2020).
myocardial hypertrophy (1 paper, 2023). "Moreover, cardiac H&E staining suggested that circ-Ntrk2 knockdown could correct the pathological changes in HYP-induced myocardial hypertrophy and could be inhibited after exogenous supplementation with miR-296-5p antagomir." (PMID 36915149, 2023).
nasal polyps (1 paper, 2022). "However, NTRK2, which was more highly expressed in adult compared to pediatric basal cells, has previously been associated with basal cell function as it was upregulated in basal cells isolated from human nasal polyps compared with basal cells from the normal nasal epithelium." (PMID 36388965, 2022).
Pan (1 paper, 2023). "The relative proportion of NTRK1, NTRK2 and NTRK3 fusions varied across Pan Cancer cohorts but NTRK3 fusions were generally the most frequent." (PMID 36914665, 2023).
pneumococcal infection (1 paper, 2014). Infections with bacteria of the species streptococcus pneumoniae. "This wide range of Ntrk2 functions places this gene in a central position linking airway smooth muscle, nervous and immune system, three areas where differences were found between resistant and susceptible strains during pneumococcal infection." (PMID 24594938, 2014).
respiratory failure (1 paper, 2019). The significant impairment of gas exchange within the lungs resulting in hypoxia, hypercarbia, or both, to the extent that organ tissue perfusion is severely compromised. "The neurotrophin BDNF binds with high affinity to NTRK2 and plays a prevalent role in neuronal plasticity.Null mutants for studying BDNF or NTRK2 deficiency have been unsuccessful in rodent models due to developmental abnormalities and respiratory failure leading to postnatal lethality." (PMID 30765816, 2019).
Right ventricular hypertrophy (1 paper, 2023). In this case the right ventricle is more muscular than normal, causing a characteristic boot-shaped (coeur-en-sabot) appearance as seen on anterior- posterior chest x-rays. "It was confirmed that circ-Ntrk2 knockdown could prominently inhibit PASMCs proliferation and relieve pulmonary vascular remodelling and right ventricular hypertrophy in vivo and in vitro." (PMID 36915149, 2023).
ROHHAD syndrome (1 paper, 2024). "TRKB is encoded for by neurotrophic receptor tyrosine kinase 2 (NTRK2), and neither variants in BDNF nor NTRK2 have been found in individuals with ROHHAD syndrome." (PMID 39595809, 2024).
Splenomegaly (1 paper, 2022). Abnormal increased size of the spleen. "This marker falls within NTRK2, a gene whose mouse ortholog has been implicated in splenomegaly in L. donovani infection." (PMID 35974006, 2022).
treatment resistant depression (1 paper, 2023). Unipolar depression that does not respond to commonly used treatments, typically defined as lack of response to at least two appropriate antidepressant treatments. "NTRK2 gene polymorphism has been associated with an increased risk of developing Treatment Resistant Depression (TRD), with a reduction of HAM-D21 score." (PMID 37047730, 2023).
tumor (258 papers, 2007 to 2026). "Another receptor that, when overexpressed, is related to tumor malignancy is Tropomyosin Related Kinase B (TRKB), encoded by the NTRK2 gene." (PMID 40149887, 2025). "PC were also directly associated with tumor-specific interactions related to stem cell signaling through Bmp7_Bmpr, and proliferation and angiogenesis through Ntf3_Ntrk2." (PMID 40562749, 2025). "To generalize these findings in NPC, we conducted a meta-correlation analysis, which revealed a robust association between NTRK2 and stemness features across multiple patient tumor datasets." (PMID 40133476, 2025). "This is not due to insufficient “baiting” of NTRK2 as probes to all kinase domain encoding exons of NTRK2 as well as intron 12 were used and we have successfully identified NTRK2 fusions from other tumor types in our database." (PMID 35506567, 2022). "Gene fusions involving NTRK1, NTRK2 or NTRK3—which encode the TrkA, TrkB and TrkC receptor kinases, respectively—are found throughout a wide range of human neoplasms." (PMID 33921435, 2021). "Based on the spinal location, NTRK2 rearrangement, and heterogeneous 1p loss in tumor cells, we retained the diagnosis of DLGNT." (PMID 31677015, 2020). "Neurotrophic receptor tyrosine kinase 2 (NTRK2) is a member of the tropomyosin receptor kinase family associated with the tumor development." (PMID 31245181, 2019). "These genes included those that have been reported to be associated with the biological behaviour of tumour cells (NTRK2, MAPK8, BCOR, and PIK3R1 genes)." (PMID 31034520, 2019). "The two isoforms of PRUNE2::NTRK2 gene fusions identified in our study may, however, lead to modified or limited tumor suppressor function of PRUNE2 or even loss-of-function and consequently, a possible dominant-negative effect." (PMID 41323367, 2025). "The NTRK2 oncogene is, however, associated with tumor progression." (PMID 41323367, 2025). "It was stated that NTRK2 is associated with tumour development." (PMID 40061872, 2025). "Furthermore, it was found that NTRK2 is a risk gene and is upregulated in tumor tissues." (PMID 39351154, 2024). "We utilized an RNA hybrid capture-based NGS approach designed to detect fusions and splice variants in 55 genes including NTRK1, NTRK2, and NTRK3 fusions, resulting in a detection rate of 0.35% across a real-world, pan-tumor cohort." (PMID 40385986, 2025). "This includes low prevalence biomarkers such as NTRK1, NTRK2, and NTRK3 (NTRK1/2/3) fusions as well as higher prevalence complex biomarkers such as tumor mutational burden-High (TMB-H)." (PMID 40748987, 2025). "In the present study, the expression level of NTRK2/3 mRNA decreased significantly (P-value <.0001) in tumour samples." (PMID 40061872, 2025). "Activation of the NTRK2 and NTRK3 signalling pathways has been associated with tumour invasion, resistance to therapy, and the progression of numerous malignancies, including BC." (PMID 40061872, 2025). "The NTRK2 rearrangement was subsequently confirmed by fluorescent in situ hybridization on tumor tissue sections." (PMID 39326005, 2025). "The prognostic analysis suggests the potential important role of SOX2 and NTRK2 in NPC tumor progression, prompting further exploration of their function in NP cells." (PMID 40133476, 2025). "Screening formalin-fixed paraffin-embedded tumor material using an open-ended RNA sequencing panel revealed a novel in-frame autophagy related 16 like 1-neurotrophic receptor tyrosine kinase 2 (ATG16L1::NTRK2) fusion gene." (PMID 39326005, 2025). "Our findings show that the TRIM24::NTRK2 fusion initially had oncogenic abilities, but this became less imperative as the tumor evolved." (PMID 41331048, 2025). "We identified a rare TRIM24::NTRK2 fusion in the primary tumor, which enabled a targeted TRK-inhibitor treatment." (PMID 41331048, 2025). "NTRK2 plays an essential role in tumor migration and tumorsphere formation, with this function potentially related to E-cad levels in NPC43 cells." (PMID 40133476, 2025).